HMGB1 (high mobility group box 1)
Diseases named in the same sentence as HMGB1 in open-access papers (continued):
Sharing a sentence is not in itself a finding about the gene and the disease.
cancer (continued). "The binding of HMGB1 to RAGE is thought to stimulate proliferation and differentiation of cancer cells." (PMID 25986235, 2015). "Exposure to anthracylines was sufficient to induce translocation of calreticulin, HSP70 and HSP90 to the cell surface, and HMGB-1 release at later time point, but the clinical implications of ICD in these cancer types warrants further analysis." (PMID 25688334, 2015). "In this context, it is worth noting that cancer cells exposing CALR, secreting ATP, producing type I IFNs but releasing limited amounts of HMGB1 as they respond to a lethal stimulus in a suboptimal manner fail to elicit adaptive immune responses." (PMID 25964783, 2015). "At the light of HMGB1 effect played on miRNAs 221 and 222 expression and considering that they have been shown to inhibit PTEN mRNA in many human cancers, we studied the expression of PTEN after treatment of cells with HMGB1 for up to 72 h." (PMID 26106610, 2015). "RAGE was the first receptor demonstrated to bind HMGB1, and the binding of HMGB1 to RAGE stimulates proliferation and differentiation of cancer cells as well as tissue regeneration." (PMID 25986235, 2015). "Subsequently, it was shown that HHP-treated mammalian cancer cell lines undergoing apoptosis can release HSP70 and HMGB1, while retaining their immunogenicity in vivo." (PMID 26834740, 2015). "In fact, the experience we have gained with the BALB-neuT model suggests that some of the molecules released by MSCs, such as IL-6, TGF-β, and HMGB1, are key molecules in CSC self-renewal and cancer progression." (PMID 25136593, 2014). "Several PRR, in particular TLRs and RAGE, are expressed in cancer cells and share distinct DAMP ligands such as HMGB1 and S100 proteins." (PMID 24723911, 2014). "Recent studies have provided direct evidence that MSCs are recruited in TME by a broad range of soluble factors which are secreted by cancer cells and CSCs, including IL-6, VEGF and bFGF, CCL2, SDF-1α, and HMGB1." (PMID 25136593, 2014). "Second, HMGB1 regulates the expression of HSPB1 (heat shock 27 kDa protein 1) in immortalized mouse embryonic fibroblasts and cancer cells." (PMID 25126737, 2014). "On the other hand, inflammatory condition induced by HMGB1 and stimulation of APC can be of significance for triggering specific immune response directed against cancer cells." (PMID 24487722, 2014). "On the other hand, inflammatory condition induced by HMGB1 and stimulation of antigen-presenting cell (APC) maturation can trigger immune response against cancer cells." (PMID 24487722, 2014). "Although HMGB1 has been studied more extensively, considerably less is known regarding HMGB2 in the study of cancer, particularly its relevance in carcinogenesis." (PMID 23426143, 2013). "Overexpression of HMGB1 and HMGB2 has been observed in several human cancer types, including hepatocellular, skin squamous cell, prostate, gastrointestinal and breast carcinomas." (PMID 23426143, 2013). "HMGB1 secretion and its binding to cell membrane receptors including the receptor for advanced glycation end products (RAGE) appear to be important in cancer progression." (PMID 22496788, 2012). "Serum HMGB1 levels were elevated in stage I cancer compared to those of CEA, whereas serum CEA levels were higher in advanced-stage cancer." (PMID 22496788, 2012). "HMGB1 were significant differences among Edmondson grade, TNM stage and Cancer of the Liver Italian Program score." (PMID 20579387, 2010). "As a key nonhistone DNA-binding protein, HMGB1 is critical for the modulation of autophagy in multiple types of cancer cells, as outlined by many studies." (PMID 41164196, 2025). "In radioimmunotherapy using internal radiopharmaceutical therapy, the release of DAMPs, including HMGB1, from damaged cancer and normal cells has not been examined in comparison with that observed for radioimmunotherapy using external radiotherapy." (PMID 40583575, 2025).
cancer (continued). "Recent work has revealed that specific stimuli such as HMGB1 and CTSC initiate distinct signaling modules, underscoring the context-dependent heterogeneity of NETosis across infection, autoimmunity, thrombosis, and cancer." (PMID 41335221, 2025). "Additionally, radiation-induced HMGB1 secretion activates CAFs via TLR4/PI3K-AKT to suppress apoptosis and drive cancer radioresistance, an effect reversed by HMGB1 inhibition." (PMID 41465435, 2025). "Additionally, DBF4B showed a positive correlation with HMGB1, BTN3A1, and VEGFA across various cancers." (PMID 40535802, 2025). "Based on these findings, we hypothesized that metformin’s interaction with HMGB1 would interfere with its binding to the receptor for advanced glycation end products (RAGE), thereby influencing cancer metastasis." (PMID 40277915, 2025). "It was found that targeting High-mobility group box 1 (HMGB1) could remodel TME and enhance its efficacy in combination with anti-PD-1/PD-L1 immunotherapy for anti-cancer purposes." (PMID 40557151, 2025). "For instance, HMGB1, HMGB2, and MS4A1 were hypomethylated and highly expressed, whereas hypermethylation of genes such as LDB1, NDUFS2, and POU2F2 led to their reduced expression, reinforcing the impact of DNA methylation on gene dysregulation in cancer." (PMID 40396172, 2025). "HMGB1 promotes HCC resistance to sorafenib by stimulating the downstream MAPK cascade through Erk1/2 phosphorylation, activating autophagy, and eventually inhibiting cancer cell apoptosis." (PMID 40331953, 2025). "Additionally, in tumor-bearing mice, glycyrrhizin suppressed lung cancer growth by inhibiting the HMGB1 and JAK/STAT pathway activity, both of which are involved in cancer cell migration and invasion." (PMID 40149916, 2025). "While such regulation influences genome stability and repeat expansion, there is currently no direct evidence linking HMGB1-mediated BER to therapy resistance in cancer, warranting further investigation." (PMID 41465435, 2025). "Extracellular HMGB1 interacts with receptors, such as toll-like receptor 4 and receptor for advanced glycation end products (RAGE), promoting cell proliferation, survival, and migration in cancer cells." (PMID 40389855, 2025). "Furthermore, metformin lowers HMGB1 and RAGE protein levels, disrupting the positive feedback loop that promotes cancer aggressiveness." (PMID 40277915, 2025). "RO-treated animals showed delayed malignant transformation, with no carcinomas at week 16 and increased expression of caspase-9, calreticulin, HMGB1, IFN-γ, and GM-CSF, indicating transient activation of antitumor immune responses." (PMID 40943044, 2025). "HMGB1, HSP90, S100A9, and ATP were emphasized as the expression DAMPs in cancer patient serum." (PMID 39768997, 2024). "While the individual functions of CXCL12 and HMGB1 in cancer have been extensively explored, the role of the CXCL12/HMGB1 heterocomplex remains unclear." (PMID 38803493, 2024). "In comparison with PBS, LEV@DOX@REV significantly increased the secretion of ATP into the extracellular milieu of cancer cells (P < 0.05), and there was a significant difference between LEV@DOX@REV and PBS regarding HMGB1 release from the nucleus into the extracellular milieu." (PMID 38868091, 2024). "Our results suggested that HMGB1 and HSP90 could potentially serve as predictive biomarkers of metastatic status in cancer patients." (PMID 39768997, 2024). "To determine whether cell death caused by CKS1 is immunogenic, we evaluated the amount of ATP and HMGB-1 released in the culture media upon CKS1 treatment of 4T1 and CT26 cancer cells." (PMID 38565596, 2024). "For example, chemotherapy-induced immunogenic cell death (ICD) leads to cells exposing or releasing damage-associated molecular patterns (DAMPs), such as HSP70, calreticulin, ATP, high-mobility group box 1 (HMGB1), type I IFN, and cancer cell-derived nucleic acids." (PMID 39103698, 2024).
cancer (continued). "Feedback loops between HMGB1 and RAGE have been observed during the progression of cancer." (PMID 39335163, 2024). "Further exploration of HMGB1’s regulatory mechanisms and the effects of PGCC-derived neosis on cancer metastasis could provide new insights into post-treatment cancer recurrence." (PMID 39055650, 2024). "The involvement of HMGB1 in cancer is complex, and its precise mechanisms are not yet fully understood." (PMID 38725632, 2024). "ISCA1 was correlated with ENTPD1, HMGB1, TLR4, and TGFBR1 in more cancers." (PMID 39766805, 2024). "On the other hand, HMGB1 potentially augments the expression of transcription factors like extracellular signal-regulated kinase (ERK)-1/2 and p38 in lung cancer progression, regulating cancer cell proliferative capacity and tumor growth." (PMID 39682695, 2024). "Aberrant release of HMGB1 has been shown in human cancers, and HMGB1 mediates the epithelial to mesenchymal transition (EMT), which is necessary for invasion and migration in cancers from epithelial origin." (PMID 37110415, 2023). "Furthermore, the inhibition of high-mobility group protein B1 (HMGB1) is a target of miR-129-5p and, according to some studies, results in cancer development in cases of dysregulation." (PMID 37509697, 2023). "It is likely that the dynamics of HMGB1 may vary with NACT regimes and cancer subtypes and more studies are needed to elucidate the correlation in various NACT regimens." (PMID 37684327, 2023). "Hence the metabolic shift of cancer cells via AGEs can be attributed to instigation of inflammation via RAGE and HMGB1, which in turn fuel the metabolic activity of cancer cells for accelerated energy generation." (PMID 37970208, 2023). "The observation that Lf-GL treatment shows some cytotoxicity to cancer cells in the absence of HMGB1 is an interesting finding that highlights the potential complexity of the Lf-GL complex's mechanism of action." (PMID 37210579, 2023). "S100A8/A9 and HMGB1 are potential biomarkers for the accumulation of MDSCs and their neutralization and/or the inhibition of RAGE may enhance cancer immunotherapies." (PMID 36831371, 2023). "HMGB1, as a DAMP released by cancer cells, can efficiently activate TLR4." (PMID 36911674, 2023). "As a result of SCNV of NRGs in pan-cancer, we found SCNV gain in DNASE1, HMGB1 and PIK3CA." (PMID 37408763, 2023). "This interplay of AGEs-RAGE via HMGB1 and other pro-inflammatory molecules in TME forms the basis of immune evasion and cancer survival, further leading to ECM alterations via AGE-RAGE crosstalk in TME paving way for invasive phenotype and metastatic dissemination." (PMID 37970208, 2023). "Furthermore, TTFields induce the expression of immunogenic markers on cancer cells, including calreticulin (CRT) on the cell surface and the release of high mobility group box 1 protein (HMGB1), indicating immunogenic cell death." (PMID 37916157, 2023). "Vincristine exhibits anti-cancer effects by enhancing cell apoptosis, while HMGB1 exhibits the opposite role by upregulating the anti-apoptotic myeloid leukemia 1 (MCL-1) protein levels, thus contributing to the autophagy-mediated protection of cancer cells." (PMID 37511951, 2023). "Recently, it was shown that early, but not late, ferroptotic cancer cells release classical DAMPs (e.g., ATP, HMGB1) with subsequent phenotypic maturation of BMDCs." (PMID 35562364, 2022). "In addition, we measured the release of reactive oxygen species (ROS), high-mobility group box 1 (HMGB1), cytochrome c, and ATP after the treatment of cancer cells with P-113 derivatives." (PMID 35625834, 2022). "The binding of HMGB1 with RAGE through its carboxyl-terminal tail can stimulate RAGE, a criterion for cell motility; its binding to RAGE has a synergistic effect with a dominant inhibitor in stopping the progression of cancer." (PMID 36613714, 2022).
cancer (continued). "Senescence is an alternative anticancer mechanism for apoptosis-resistant cancer cells, and we have previously shown that cancer cells choose either senescence or apoptosis depending on the expression of genes such as AKT or HMGB1." (PMID 36109513, 2022). "Moreover, the truncated form of HMGB1 (named hereafter as HMGB1-ΔC) retains the capacity of the full-length protein HMGB1-fl to interact with PKM2 and to perturb the metabolism of cancer cells." (PMID 35887213, 2022). "Despite the incomplete identification, results from the current study suggest that cancer cells may actively participate in the processes of NET formation through their release of promoting molecules, with HMGB1 being one such candidate." (PMID 36012397, 2022). "Dying cancer cells emit DAMPs such as CRT, HMGB1 and ATP, which are efficiently engulfed by BMDCs." (PMID 35562364, 2022). "For example, extracellular HMGB1 stimulates the release of pro-inflammatory cytokines such as IL-6 and IL-8 by triggering MAPK- and MyD88-dependent NF-κB pathways, subsequently facilitating cancer cell proliferation, angiogenesis, EMT, invasion and metastasis." (PMID 35927755, 2022). "In this work, we report that the deletion of the C-terminal tail of HMGB1 increases its activity towards a large panel of cancer cells without affecting the viability of normal immortalized fibroblasts." (PMID 35887213, 2022). "Perhaps HMGB1 is an even more promising marker in particular types of cancer where no extensive toxicity is to be expected during radiotherapy." (PMID 34671818, 2022). "In summary, our study shows that the deletion of the C-terminal acidic tail of HMGB1 increases the in vitro anticancer activity of the recombinant protein towards a large panel of cancer cells without affecting normal immortalized fibroblasts." (PMID 35887213, 2022). "To summarize, A549 and T24 cancer cells may accelerate or promote the ongoing NET formation in a cellcontact-independent mechanism, while extracellular released HMGB1 could be the candidate responsible for such an effect." (PMID 36012397, 2022). "Indeed, MDSCs secrete HMGB1 and make up the immunosuppressive TME, which protects cancer cells from immune detection and promotes cancer survival and progression." (PMID 35408786, 2022). "In brief, DUSP1, ZFP36, SLC2A3, HMGB1, STAT3, MT3, and ALOX5 were all FRGs that might be involved in cancer development and immune regulation." (PMID 36131791, 2022). "In our work, we showed the exposure of calreticulin in a subpopulation of ferroptotic cells shortly before their rupture, as well as ATP, HMGB1, CXCL1, TNF and IFN-β release in the course of a drug- and genetically induced models of ferroptosis in cancer cells." (PMID 35760796, 2022). "Cancer cells undergoing ICD require cell surface calreticulin (CRT) exposure, induction of EIF2α-dependent reticulum stress, high mobility group box 1 (HMGB1) and ATP release, and the expression of type 1 IFNs (Ifnα1 and Ifnβ1) and chemokines (Cxcl 9 and Cxcl 10)." (PMID 36090972, 2022). "If cancer cells experience stress, injury, or death after PTT, they release DAMPs, such as heat shock proteins (Hsp), adenosine triphosphate (ATP), high-mobility group box 1 (HMGB1), and calreticulin (CRT)." (PMID 35454950, 2022). "Moreover, disruption of the interplay between cancer cells and neutrophils towards NET formation involving cancer cell-derived HMGB1 was found via a human A549 and T24 cancer cell study." (PMID 36012397, 2022). "It is conceivable that crosstalk between the C6-inhibiting HMGB1-RAGE signaling pathway and DNA damage may occur in alterations of gene regulation, including suppression of inflammation in the TME and cancer cell proliferation and induction of apoptosis." (PMID 35408786, 2022).
cancer (continued). "Among 33 kinds of cancers, HMGB1/2/3 expression was significantly positively correlated with the MSI of 6 (18.2%), 10 (30.3%), and 10 (30.3%) types of cancers but negatively correlated with the MSI of 2 (6.0%), 1 (3.0%), and 1 (3.0%) types of cancers respectively." (PMID 34777483, 2021). "Particularly, cancer cells underwent senescence selectively rather than apoptosis depending on HMGB1 expression." (PMID 33558529, 2021). "As for the TMB, HMGB1/2/3 expression was significantly positively correlated with the TMB of 4 (12.1%), 11 (33.3%), and 16 (48.5%) kinds of cancers but negatively correlated with the TMB of 4 (12.1%), 2 (6.0%), and 2 (6.0%) kinds of cancers, respectively." (PMID 34777483, 2021). "Therefore, in this study, we investigated the relationships between HMGB1 and STING in senescence in cancer and other cells." (PMID 33558529, 2021). "HMGB1 can bind to Toll-like receptor 4 (TLR4), promote the release of proinflammatory cytokines from monocytes/macrophages and regulate the function of endothelial and cancer cells." (PMID 34588987, 2021). "HMGB1 is also associated with senescence, although its role in cGAS/STING-dependent senescence in cancer cells has not been determined." (PMID 33558529, 2021). "Another study demonstrated that the release of RAGE triggered by ferroptotic cells was necessary for HMGB1-mediated tumor necrosis factor (TNF) production in macrophages, suggesting that ferroptotic cancer cells could be immunogenic in nature." (PMID 33819918, 2021). "Notably, HMGB1 is highly involved in various levels of inflammation and promotes the activation of CD4 T cells by stimulating the cross-presentation of cancer cell neoantigens to the immune system by DCs." (PMID 34599143, 2021). "The 13q12.3 amplification in C1 contained HMGB1, which could promote the development of MDSC and the metastasis of cancer cells." (PMID 35223867, 2021). "Our results provide insights into the function of HMGB1 in STING-dependent senescence, which could be applicable to cancer prevention." (PMID 33558529, 2021). "Furthermore, in numerous cancers chronic inflammation via the HMGB1-RAGE signaling pathway has been shown to change their TME and stimulate the development of cancer." (PMID 33805209, 2021). "Though these studies have indicated that HMGB1 regulates filopodia formation and controls cancer cell migration, the mechanism of action has not been well-investigated." (PMID 33807275, 2021). "Therefore, in this study, we evaluated the role of HMGB1 and its relationship with the STING pathway in genotoxic stress-induced senescence in cancer cells." (PMID 33558529, 2021). "The suppression effect of this compound on the HMGB1-RAGE-ERK 1/2 signaling pathway may be involved in blocking the generation of TEM, anti-cancer activity, and exerting protective effects against cancer." (PMID 33805209, 2021). "A strong nuclear HMGB1 in BO epithelium in random sampling biopsies should raise suspicion of progression to dysplasia or cancer even although that progressive neoplastic focus has not been sampled." (PMID 31831860, 2020). "Endogenous HMGB1 also appears to play a key role in the development of CIPN in rats or mice treated with cancer chemotherapeutics, such as paclitaxel, oxaliplatin, and vincristine, considering the complete prevention of CIPN by inactivation of HMGB1 with HMGB1-nAb or TMα." (PMID 33396481, 2020). "Among nine candidate oncogenes, high expression of four genes including RFTN1, HMGB1, RPL24, and RPL31 were reported to be correlated with a poorer prognosis in cancers (conversely, one may say that low expression of such genes shows good prognosis)." (PMID 32039517, 2020). "In addition, HMGB1/RAGE can regulate the expression of the BCL-2 gene (B-cell lymphoma/leukemia-2 gene), which is a cancer gene with the effect of inhibiting apoptosis." (PMID 33473353, 2020).